NGFR (nerve growth factor receptor)
Diseases named in the same sentence as NGFR in open-access papers (continued):
Sharing a sentence is not in itself a finding about the gene and the disease.
tumor (continued). "To begin to develop a clinical assay based on circulating tumor derived sEVs, we opted to exploit the membranous location of CD99 and NGFR to develop a tool capable of enriching ESFT-associated sEVs from plasma in pediatric patients." (PMID 32821345, 2020). "Our study therefore uncovers a new receptor-independent, intracellular, and tumor-promoting function for NGFR." (PMID 32285119, 2020). "We conclude from these data that pre-existing NGFR-expressing cells can enrich on treatment in vivo to form a stable pool of cross-resistant tumor cells." (PMID 32770055, 2020). "Here, we identify NGFR as a novel p73 inactivator that serves as another example of an oncoprotein that can suppress p73 tumor suppressive activity." (PMID 32285119, 2020). "The objective of this study was to explore the effect of electroacupuncture with encircled needling on TNBC tumor growth, the expression of angiogenic factors, MMPs, and NGFR p75 in TNBC tumor tissue." (PMID 31839752, 2019). "Compared to them, however, while maintaining potent therapeutic effects against high-tumor burdens, the NGFR spacer technology has the advantage of being fully compatible with clinical-grade immuno-magnetic beads." (PMID 29619024, 2018). "We next sought to validate the antitumor efficacy of NGFR-enriched CD44v6 CAR-T cells by stress-testing them in vivo against high-tumor burdens." (PMID 29619024, 2018). "In accordance with the high-tumor burden setting, the antitumor effects of all three NGFR isoform-enriched CD44v6 CAR-T cells were accompanied by elevated systemic levels of human IFN-γ, in the absence of IL-6 and IL-10." (PMID 29619024, 2018). "Together these data demonstrate that purely ADC lesions derived from transplanted KRAS+ cells can transition to SCC, and that tumours can acquire the SCC TPC expression profile of Sca1+/NGFR+ upon Lkb1 deletion." (PMID 28387316, 2017). "Small interfering RNA against NGF or proNGF, anti-NGF antibodies, and inhibitors of NGFR were pro-apoptotic and anti-proliferative for cancer cells and inhibited tumor growth and invasiveness." (PMID 28679437, 2017). "For the calcium flux assay, NK cells transduced with CXCR2 or the control NGFR were stimulated with recombinant CXCL8 or conditioned RCC tumor supernatants." (PMID 28923105, 2017). "We have previously shown that NGFR+ cells in human OSCC possess the greatest tumor-initiating capacity in this malignancy and that inhibition of NGFR has profound negative effects on the ability of these tumor-initiating cells (TIC) to form tumors in vivo." (PMID 27683113, 2016). "In contrast to our findings and the oncogenic role NGFR has also been shown to exert a tumor suppressive function by repressing tumor growth in several cancers, which has been largely attributed to its receptor activity." (PMID 27282385, 2016). "Because of the diminutive size of the tumors generated from the NGFR knockdown group, we were unable to collect sufficient amounts of tumor tissues for WB and IHC staining." (PMID 27282385, 2016). "In vivo transplantation of ESM1-knockdown cells led to a significant reduction in NGFR-induced tumor growth and pulmonary metastases." (PMID 27683113, 2016). "Conversely, shRNA knockdown of ESM1 in NGFR overexpressing OSCC cells abrogated the tumor growth kinetics and the invasive and metastatic properties associated with NGFR." (PMID 27683113, 2016). "Here, we used an established murine model of OSCC and gene expression array analysis to identify ESM1 as a downstream target gene of NGFR, critical for tumor invasion and metastasis." (PMID 27683113, 2016). "Further, comparison of ESM1 expression in MOC2, MOC2-7, and MOC2-10 cells revealed a correlation with the extent of NGFR expression and the tumor growth kinetics and invasive phenotype observed in the MOC cell lines." (PMID 27683113, 2016).
tumor (continued). "Nude mice were inoculated with a mixture of HeLa cells and N1/28z- or NGFR-transduced cells (at E:T of 2:1) and we followed tumor development in the subsequent weeks." (PMID 25431955, 2014). "The N1/28z treated group displayed a statistically significant reduced tumor growth compared to the NGFR (control) group (p=3×10−5 )." (PMID 25431955, 2014). "However, in lobules with tumor invasion, NGFR+ stromal cells co-expressed the iCAF marker, PDGFRα, to a high extent (94%), while 22% of NGFR+ cells were positive for ASMA, and 34% for CD74." (PMID 41006303, 2025). "To further quantify NGFR expression in relation to progressing tumor cell invasion, we first measured NGFR abundance in morphologically unaffected lobules without inflammation and without overt acinar changes to establish an expression baseline in near-normal pancreatic lobules." (PMID 41006303, 2025). "NGFR+ stromal cells were enriched at early time points following tumor injection in mice and were more abundant in smaller human tumors, supporting a model in which stromal NGFR/NGFR expression declines as tumor invasion advances and desmoplastic stroma develops." (PMID 41006303, 2025). "In conclusion, our study defines PHOX1 as a methylation-sensitive oncogene in GC, orchestrating tumor progression through transcriptional activation of NGFR, and the PHOX1-NGFR-ERK1/2 axis may serve as a therapeutic target for metastatic GC." (PMID 41315175, 2025). "However, specimens were not all equivalently heterogeneous: a subset of deeply invasive specimens contained only tumor cells with embryonic neural-crest like states having uniform NGFR staining." (PMID 40667360, 2025). "For example, NGFR enhances autophagy induced by 5-FU to inhibit tumor growth in colorectal cancer." (PMID 40758712, 2025). "Importantly, the NGF secreted from tumor cells was received mainly by the NGFR expressed in T cells, and this NGF‐NGFR interaction contributed to the primary NGF‐NGFR communication signaling pathway network." (PMID 38204220, 2024). "Importantly, NGF secreted by tumor cells interacts with NGFR present on the membranes of the infiltrated T cells, thereby promoting the proliferation through the activation of mitotic spindle signals." (PMID 38204220, 2024). "To identify potential druggable targets, we surveyed the pan-MBM, NGFR and Ecad-specific gene sets for cell surface receptors that may serve as crucial key factors controlling tumor cell survival and maintenance." (PMID 38386085, 2024). "Nevertheless, PCA representation of MET levels in individual tumors and single-cell resolution revealed a gradual expression pattern showing distinct METhigh and METlow expressing subsets and overlapping expression with NGFR in tumor cells with intermediate levels of MET." (PMID 38386085, 2024). "Unfortunately, the expressions of NGF and NGFR were low in the tumor tissues of HCC patients, which could be the possible reason for the reduced numbers of T cells in these tissues." (PMID 38204220, 2024). "Specifically, by using in vitro and in vivo experimental models, these authors could observe that NGFR protects tumor cells from NK cell-mediated clearance by downregulating NK cell-activating ligands and lipid reprogramming." (PMID 39199632, 2024). "However, expressions of NGF and NGFR are low in tumor tissues, which is responsible for the invasive clinicopathological features and the disappointing prognosis in HCC patients." (PMID 38204220, 2024). "Quantification of the total numbers of green fluorescent protein (GFP)–positive tumor cells in single-cell suspensions of the lungs by flow cytometry confirmed increased numbers of NGFR-induced cells compared to EV control cells in mice with transferred human NK cells." (PMID 36638181, 2023).
tumor (continued). "Next, we evaluated whether NGFR-mediated ligand changes on tumor cells interfere with NK cell activation." (PMID 36638181, 2023). "Thus, we conclude that NGFR confers a survival advantage to tumor cells in the presence of human NK cells in vivo." (PMID 36638181, 2023). "Our results align with studies in which NGFR acts as a tumor promoter." (PMID 35280742, 2022). "Moreover, IL1RAP, related to oncogenic signaling and NGFR, displaying an ambivalent role in tumor progression, were upregulated in M." (PMID 35892888, 2022). "Ecad-mediated cell adhesion probably promotes different molecular traits in tumor cells as NGFR+ MBM that may exhibit Ncad (N-cadherin, CDH2) mediated cell adhesion." (PMID 36435874, 2022). "Previously, we reported that NGFR plays a role as a tumor suppressor gene, and it could be silenced by epigenetic modification." (PMID 33996571, 2021). "To determine whether tumor cell growth inhibition by NGFR was related to cell cycle arrest and apoptosis, we used flow cytometry." (PMID 33996571, 2021). "The tumor sizes of NGFR transfectants were significantly smaller than those of vector transfectants after an intraperitoneal injection of 5-FU (vector vs. NGFR: 500.9 ± 198.0 mm3 vs. 82.6 ± 36.8 mm3, P < 0.001), confirming that NGFR acts as a chemotherapeutic enhancer in CRC." (PMID 33996571, 2021). "Moreover, ESM-1 knockdown with short hairpin RNAs (shRNAs) dramatically inhibit the NGFR induced tumor growth, invasion, and metastasis in oral squamous cell carcinoma." (PMID 34109132, 2021). "As a candidate tumor suppressor, NGFR has independent prognostic potential in CRC." (PMID 33996571, 2021). "Lastly, pharmacological inhibition of NGFR restores T cell sensitivity in tumor cells." (PMID 32770055, 2020). "In this study, we showed that electroacupuncture could upregulate the expression of NGFR p75 in TNBC tumor tissues." (PMID 31839752, 2019). "When OVA-ALL cells were injected in immunodeficient NOD-SCID-IL2Rg−/− (NSG) mice, we observed comparable tumor growth as the parental cells and no loss of NGFR expression." (PMID 30042420, 2018). "We also confirmed cell surface NGFR staining in the tamoxifen-treated mouse tumours by IHC." (PMID 28387316, 2017). "In our previous studies, we observed that KRAS tumour propagating cells (TPCs) were present in both Sca1+ and Sca1- compartments, and a purely squamous model generated by bialleleic inactivation of Lkb1 and Pten (Lkb1/Pten) harboured Sca1+ and NGFR+ TPCs37." (PMID 28387316, 2017). "Consistent with previous observations that NGFR contributes to tumor-initiating capacity, the degree to which NGFR was expressed in these cell lines appeared to correlate with both tumor cell invasion and migration capacity in transwell invasion assay and tumor growth kinetics in vivo." (PMID 27683113, 2016). "Also, the average tumor weight from control cells was ~ten-fold heavier than that from NGFR-shRNA cells by the end of the experiment." (PMID 27282385, 2016). "In addition, overexpression of NGFR observed in many metastatic cancers promotes tumor migration and invasion." (PMID 27282385, 2016). "Remarkably, targeting NGFR led to the suppression of tumor cell growth in vitro and in vivo." (PMID 27282385, 2016). "But, in prostate and bladder cancers, NGFR appears to suppress tumor growth and/or metastasis." (PMID 27282385, 2016). "Furthermore, treatment of the cells with the anti-NGFR antibody resulted in significant reduction in tumor growth in vivo compared to isotype control – treated cells." (PMID 25149537, 2014).
tumor (continued). "Here, we used combined transcriptome and methylome profiling to unravel the molecular features of MBM of different progression stages showing high and low level of tumor-associated macrophages/microglia (TAMs) infiltration, irrespective of the phenotype (Ecad, NGFR)." (PMID 38386085, 2024). "Moreover, analyses of SOX10– and SOX10+MITF– tumors developed in NSG mice at molecular level suggested a profound difference between the tumor types and reflected the tumor growth difference and sustained increased expression of NGFR, JUN, and WNT5A in the SOX10+MITF– melanoma tumors." (PMID 36040798, 2022). "Tumor derived cell lines BMC1-M1 and BMC1-M4 exhibited distinct proliferative and migratory properties, probably the consequence of the loss of microenvironmental cues such as growth factors and cytokines or adhesive connections or modulation of levels of NGFR expression." (PMID 36435874, 2022). "In addition, a recent study in a population of TNBC cells reported an overexpression of NGFR/p75NTR and an interaction between NGFR/p75NTR and TrkC receptors which affects tumor growth and metastasis through the Trk MEK-ERK1-ZEB1 and PI3K-AKT signaling pathways." (PMID 36354700, 2022). "Furthermore, PaCa-derived NGF attracts Schwann cells via NGFR/p75NTR, which might be interpreted as the recruitment of nerve cells toward the tumor being the first step in PNI." (PMID 31921628, 2019). "In the human PDAC datasets, stromal cells expressing NGFR signatures (Source data) were more abundant in smaller, T1 tumors (according to clinicoradiological TNM scoring, which is based on tumor size with T1 ≤ 2 cm, T2 2–4 cm, T3 > 4 cm)." (PMID 41006303, 2025). "NGFR+ (set B) locally advanced specimens with Breslow depth >4mm were an outlier in this analysis, and had the lowest entropy of all specimens in the cohort; whether this represents a general evolution of tumor state to greater homogeneity or is a feature of a minority of specimens is not yet known." (PMID 40667360, 2025). "MRs in group I were enriched in MART1− NGFR+ tumor cells (and a brisk CD8+ T cell infiltrate was present), while group II MRs contained MART1+ NGFR− cells." (PMID 40667360, 2025). "5x106 T cells (HK2 + TCR or NGFR + TCR) were injected through the tail vein, one and two weeks after the tumor cell injection." (PMID 40181966, 2025). "This suggests that not only NGFR and Ecad but additional correlating genes may underlay cellular plasticity-related regulation of expression, hence therapeutic targeting of the MET receptor signaling pathway by small molecule inhibitors may eliminate several MET+ tumor cell subsets." (PMID 38386085, 2024). "In the present study, NGF/NGFR was correlated positively with PD‐1/PDL‐1 expression in both tumor tissue and healthy tissue, and the NGF‐NGFR communication inefficiency was demonstrated to suppress the proliferation of T cells." (PMID 38204220, 2024). "In this context, the present study revealed that NGF+ tumor cells, NGF− tumor cells, NGFR+ T cells, and NGFR− T cells appeared simultaneously in HCC patients." (PMID 38204220, 2024). "After the successful formation of the subcutaneous tumor, the immune system was reconstructed via an injection of CD3+ T cells (1*106), which had been separated from PBMCs and transfected with NGFR‐sh‐rAd, and PD‐1 mAb." (PMID 38204220, 2024). "We assessed the infiltration of endogenous CD8 + T cells (CD8 + NGFR-) and CAR-T cells (NGFR + ) on both local and abscopal tumor slides." (PMID 39578426, 2024). "In detail, we observed the presence of YAP1+ (Fig EV3E′ and F′) and p75 NGFR+ (Fig EV3E′′ and F′′) cells in SHH MB‐derived PDOs (tumor #9 and #10)." (PMID 38037472, 2023).
tumor (continued). "Loss of EZH2 facilitates reduction of H3K27me3 levels and activation of clusterin (CLU) and nerve growth factor receptor (NGFR), which are tumor suppressive genes in NB." (PMID 35392988, 2022). "Immunohistochemistry using various tumor stem cell-specific markers, including acetaldehyde dehydrogenase 1, CD44, CD133, Nestin, NGFR, and SOX9, revealed short spindle-positive cells scattered within the tumor, suggesting the involvement of tumor stem cells." (PMID 36187098, 2022). "With the combination, there was also an upregulation of nerve growth factor receptor (NGFR), which acts as a tumor suppressor in the bladder, stomach, liver, colorectal, and prostate." (PMID 35800820, 2022). "The results revealed that most of the SRGs were differentially expressed and most of them were found increased in tumor tissues except for KIT, NGFR, SOX2 and KLF4 (sFigure 2A)." (PMID 34587919, 2021). "Unsurprisingly, tumor cells express various receptors, such as tyrosine kinase receptor A (TrkA), TrkB, and NGF receptor (NGFR), when responding to different neuroactive molecules to activate downstream pathways." (PMID 33846291, 2021). "While mice treated with either Panobinostat or Mocetinostat showed reduced xenograft tumor growth, the expression of established invasiveness genes, such as AXL or NGFR was upregulated." (PMID 34417458, 2021). "Earlier studies identified NGFR as a potential biomarker for MICs, as it was highly expressed in MICs and was important for MIC-derived tumor growth." (PMID 32686661, 2020). "To explore these populations in the transplanted tumours, we collected tumours from each mouse, dissociated and analysed EpCAM+/CD31−/CD45− cells for expression of NGFR and Sca1." (PMID 28387316, 2017). "The nerve growth factor receptor (NGFR) has been observed to be expressed on a subset of cells in OSCC, and NGFR+ cells have greater tumor-initiating capacity in vivo." (PMID 27683113, 2016). "It is not surprising that tumor cells express various receptors, including tropomyosin receptor kinase (Trk)A, TrkB, and nerve growth factor receptor (NGFR), in response to these neuroactive substances, activating downstream signaling pathways." (PMID 40940782, 2025). "While most tumor meta-programs exhibited melanocytic differentiation (high MITF and CTNNB1), two meta-programs-Respiration and Stress-expressed dedifferentiation markers including AXL, SOX9, EGFR and NGFR." (PMID 40890106, 2025). "Histological and immunohistochemical analyses confirmed the tumor’s myofibroblastic origin, characterized by positivity for markers such as vimentin, glial fibrillary acidic protein (GFAP), nerve growth factor receptor (NGFR), alpha-smooth muscle actin (SMA), and muscular actin (HHF35)." (PMID 40559758, 2025). "Stromal NGFR expression was highest in injured lobules exhibiting mild to moderate atrophy, both with and without detectable tumor invasion, but declined sharply in the presence of tumor invasion accompanied by advanced atrophy." (PMID 41006303, 2025). "To quantify NGFR protein expression in relation to tumor invasion in human PDAC, we utilized the ML–augmented annotations to measure NGFR surrounding individual tumor cells (n = 5103), taking into account their distance from the tumor-exocrine invasive edge." (PMID 41006303, 2025). "Moreover, ChIP analysis of tumor tissues revealed that the recruitment of BACH1 to the promoters of CEMIP, CXCL14, and NGFR was markedly enhanced in tumors from the Keto diet group compared to the Ctrl group." (PMID 38838145, 2024). "We observed a high concordance with immune cell-related but not tumor cell-related genes (NGFR, MITF, MLANA, SLC45A2) and correlation with expression of PDCD1LG2 and SUSD3, irrespective of the side of metastasis." (PMID 38386085, 2024).